PTGS1 (prostaglandin-endoperoxide synthase 1)
Diseases named in the same sentence as PTGS1 in open-access papers (continued):
Sharing a sentence is not in itself a finding about the gene and the disease.
Chronic colitis (1 paper, 2010). A chronic inflammatory disease of the large intestine (colon, cecum and rectum). "In wt mice with chronic colitis, IL-23a, IL-13, NF-kB2, PTGS1, SMAD3 and SMAD7 (P≤0.05) were significantly down-regulated, with the largest variations affecting the expression of IL-23a and IL-13 (100- and 10-fold)." (PMID 20706593, 2010).
chronic cystitis (1 paper, 2023). Recurrent infections of the urinary bladder. "PTGS1 was associated with dyspepsia and chronic cystitis and contributed to the maintenance of the mucus barrier and mucosal blood flow in the stomach." (PMID 37375548, 2023).
chronic heart failure (1 paper, 2013). "Ptgs1 can mediate endothelial dysfunction under oxidative stress in chronic heart failure." (PMID 24564975, 2013).
colon adenoma (1 paper, 2017). An adenoma that arises from the colon.
colorectal adenoma (1 paper, 2025). An adenoma that arises from the colon or rectum. "Previous studies have also reported a lack of association between this SNP of the PTGS1 gene and other cancers, such as colorectal adenoma." (PMID 40184332, 2025).
colorectal polyp (1 paper, 2023). "The PTGS1 SNP rs4837960 is in LD (R2 = 0.93) with another PTGS1 SNP rs3842787, which has been reported to interact with NSAID use for cancer risk, although null findings were reported for this SNP in the UKCAP colorectal polyp prevention trial." (PMID 37756582, 2023). "The association of PTGS1 SNP rs4837960 and PTGS2 SNP rs2745557 with colorectal polyp risk reduction by aspirin has not been reported previously." (PMID 37756582, 2023). "None of the PTGS1, PTGS2, or HPGD SNP genotypes, including rs4837960 and rs2745557, reached univariate statistical significance for a difference in total colorectal polyp number or adenomatous polyp number between individuals who received either active EPA or placebo EPA." (PMID 37756582, 2023).
coronary heart disease (1 paper, 2024). "Smoking, coronary heart disease, and PTGS1 rs10306114 (A>G) AA/AG + GG were independently associated with aspirin recurrence in patients with IS in the Chinese population." (PMID 38728491, 2024). "Our results showed that polymorphisms at PTGS1 rs10306114 (A>G) AA/AG + GG, smoking, and coronary heart disease were independently associated with IS recurrence of IS treated with aspirin." (PMID 38728491, 2024). "We identified that smoking, coronary heart disease, and the polymorphism at PTGS1 rs10306114 (A>G) AA/AG + GG were independently associated with IS recurrence in Chinese patients." (PMID 38728491, 2024). "Smoking (OR = 5.904), coronary heart disease (OR = 7.067), and PTGS1 rs10306114 (A>G) AA/AG + GG (OR = 2.528) were independently related factors for the recurrence in patients treated with aspirin." (PMID 38728491, 2024).
diabetic nephropathy (1 paper, 2021). "Increased expression levels of PTGS1 are associated with the progression of diabetic nephropathy suggesting that these are the potential genes, interacting with our target compounds, which are dysregulated in diabetic kidney diseases." (PMID 34367469, 2021). "Among them, CAT and OGG1 are downregulated, and CASP3, COMT, CYP1B1, DPYD, NQO1, and PTGS1 are upregulated in diabetic kidney disease (DKD) tubuli." (PMID 34367469, 2021).
Dysmenorrhea (1 paper, 2025). Pain during menstruation that interferes with daily activities. "Six essential oil components could be associated with chronic pain, acute pain, musculoskeletal pain, visceral spasms, and dysmenorrhea by acting on four protein targets, including CHRM1, PTGS1, PTGS2, and SLC6A2." (PMID 40729010, 2025).
functional dyspepsia (1 paper, 2023). "Notably, PTGS1 and PTGS2 exhibited the strongest associations with functional dyspepsia." (PMID 37375548, 2023). "Fourteen genes corresponding to two gene sets were identified, and the functional dyspepsia-related genes targeted by the activated F. fructus compound were ADRA2A, BDNF, CCK, CRP, GCG, JUN, Kcnh2, PTGS1, PTGS2, Pyy, SLC6A4, and TRPV." (PMID 37375548, 2023). "In addition, it was found that there was a therapeutic effect on functional dyspepsia through a mechanism related to the interaction between seven major active ingredients of F. fructus, such as oleic acid and β-sitosterol, and 12 functional dyspepsia-related genes, including PTGS1 and PTGS2." (PMID 37375548, 2023).
gastric cancer (1 paper, 2021). A primary or metastatic malignant neoplasm involving the stomach. "The compounds with high recommendation value in the network mainly have the highest acacetin, wogonin, baicalein, Salvigenin, and Moslosooflavone value ranking of gastric cancer disease-related targets mainly NOS2, PTGS1, PTGS2, DPP4, and so on." (PMID 34421596, 2021).
gastroenteritis (1 paper, 2018). An inflammatory disorder that affects the upper and lower gastrointestinal tract. "The interactions among these targets and PTGS1, may relieve gastroenteritis and counteract possible adverse effects." (PMID 30687082, 2018).
gastrointestinal bleeding (1 paper, 2021). "Logistic regression model for genetic variants in PTGS1 and NOS3 genes in low-dose aspirin and nonsteroidal anti-inflammatory drug users, and risk of upper gastrointestinal bleeding secondary to complicated peptic disease." (PMID 34290607, 2021).
glaucoma (1 paper, 2022). Increased pressure in the eyeball due to obstruction of the outflow of aqueous humor. "To date, the response to latanoprost of patients with glaucoma and ocular hypertension, is reported to be associated with the genetic polymorphism of seven genes (ABCB1, SLCO2A1, AFAP1, GMDS, PTGS1, MRP4, and PTGFR)." (PMID 36313286, 2022). "Rs1045642 in ABCB1, rs4241366 in SLCO2A1, rs9503012 in GMDS, rs10306114 in PTGS1, rs11568658 in MRP4, rs10786455 and rs6686438 in PTGFR were reported to be positive with the response to prostaglandin analogs in patients with glaucoma." (PMID 36313286, 2022).
gout (1 paper, 2022). A condition characterized by painful swelling of the joints, which is caused by deposition of urate crystals. "In addition, our experiments showed that Simiao powder certainly regulates the expression of PPAR-γ, PTGS1, IL-6 and Bcl2 mRNA in ankle tissue in hyperuricemic-gout mice." (PMID 35672755, 2022). "Furthermore, Simiao powder certainly regulates the expression of PPAR-γ, PTGS1, IL-6 and Bcl2 mRNA in ankle tissue in hyperuricemic-gout mice." (PMID 35672755, 2022). "In addition, the main characteristic chemical components of Simiao Powder have good binding ability with IL-6, PTGS1, PPARG and BCL2 targets, which indicates that the active components of Simiao Powder can effectively treat gout by combining with core targets." (PMID 35672755, 2022).
Headache (1 paper, 2021). Cephalgia, or pain sensed in various parts of the head, not confined to the area of distribution of any nerve. "SNPs in pharmacodynamic targets have been to a lesser extent linked with side drug adverse effects in headaches, but examples of such variants can be found in the COX 1 gene (PTGS1; aspirin) or in OPRM1 (opioids) or in voltage-gated calcium channels (verapamil)." (PMID 35222013, 2021).
hearing loss (1 paper, 2022). "Finally, two genes, Ptgs1 and Prg2, are associated with inflammatory responses but not previously associated with hearing loss." (PMID 35454087, 2022).
Hepatitis (1 paper, 2023). Inflammation of the liver. "In HBV-induced hepatitis, the expressions of MAPK1, PTGS1, PTGS2, PLA2G4A, and TLR4 increased significantly." (PMID 37741847, 2023).
inflammatory bowel disease (1 paper, 2025). A spectrum of small and large bowel inflammatory diseases of unknown etiology. "ITGA2B, F2RL3, PTGS1, and ADCY5 were associated with the platelet activation pathway, while IL18 was linked to inflammatory bowel disease (IBD) and the cytokine–cytokine receptor interaction pathways." (PMID 41157169, 2025).
Insulin resistance (1 paper, 2025). Increased resistance towards insulin, that is, diminished effectiveness of insulin in reducing blood glucose levels. "Among these, PTGS1 and PTGS2 are known to exacerbate chronic inflammation by promoting PGE2 synthesis, which stimulates androgen secretion from theca cells, thus aggravating insulin resistance and metabolic dysregulation." (PMID 41267865, 2025).
kidney stones (1 paper, 2020). "A major finding of this study is that LCN2 plays a role in promoting kidney stones through regulation of the ERK signalling pathway and regulation of expression of PTGS1 and other kidney stone-related genes involved in the process of kidney stones." (PMID 33277533, 2020). "Based on the results of the data set analysis, PTGS1, GPX3 and MMD were also highly expressed in the samples of kidney stones." (PMID 33277533, 2020). "Some previous studies have shown that LCN2, PTGS1, GPX3 and MMD may play a role in the development and progression of kidney stones." (PMID 33277533, 2020).
leiomyoma (1 paper, 2014). A well-circumscribed benign smooth muscle neoplasm characterized by the presence of spindle cells with cigar-shaped nuclei, interlacing fascicles, and a whorled pattern. "Of the genes under investigation, 23 were down-deregulated (pro-angiogenic and some anti-angiogenic factors) and five were up-regulated (e.g. PTGS1 which is expressed at very low levels in leiomyomas but moderately higher levels in PTSMT)." (PMID 24398114, 2014). "Compared to leiomyomas, only a few pro-angiogenic factors such as TYMP, ANGPTL2 and PTGS1 were increased in PTSMT." (PMID 24398114, 2014).
liver diseases (1 paper, 2023). "PTGS1 had both cyclooxygenase and peroxidase activities and regulated oxidative stress and inflammation involved in drug-induced liver injury, non-alcoholic fatty liver disease, and other liver diseases." (PMID 37833954, 2023).
migraines (1 paper, 2025). "PTGS2, PTGS1, PPARG, ADRB2, GABRA1, and NOS3 are potential targets for the treatment of migraines using ginkgo seeds due to their advantageous values." (PMID 41009787, 2025).
nephrosclerosis (1 paper, 2023). Hardening of the kidney due to infiltration by fibrous connective tissue (fibrosis), usually caused by renovascular diseases or chronic hypertension. "We aimed to determine whether genetic variability represented by 38 tag-SNPs in genes of the cyclooxygenase pathway (PTGS1, PTGS2, PTGES, PTGES2 and PTGES3) leading to prostaglandin E2 (PGE2) synthesis, modified CV traits and events in 493 nephrosclerosis patients." (PMID 36690661, 2023).
prostatic diseases (1 paper, 2025). "The focus was on examining the association of certain SNPs in the PTGS1 and PTGS2 genes with prostatic diseases, as the enzymes encoded by these genes are linked to inflammation, mitogenesis, and neoplasm." (PMID 40184332, 2025).
renal fibrosis (1 paper, 2022). A final common manifestation of a wide variety of chronic kidney diseases characterized by glomerulosclerosis and tubulointerstitial fibrosis. "The results suggested that 17 core compounds such as quercetin, kaempferol, luteolin, naringenin, and 23 core targets such as NCOA2, HSP90AA1, and PTGS1 might play an important role in JPYSF-treated renal fibrosis." (PMID 35656312, 2022).
slow (1 paper, 2018). "Patients with slow transit constipation (STC) have lower PTGS1 protein and mRNA than controls." (PMID 29632490, 2018).
virus infection (1 paper, 2022). "tBHQ significantly changes the gene activities of genes that are involved in immune responses against virus infection, such as interferon signaling, prostaglandin synthesis (Ptgs1/2), and apoptosis (Dusp10)." (PMID 35629310, 2022).
tumor (47 papers, 2008 to 2025). "RTT tumours deficient in Ptgs1 and Ptgs2 (Ptgs1/2) displayed reduced PGE2 levels that were comparable to those of NTT tumours and increased T cell infiltration." (PMID 39604727, 2025). "Quantification of TIL populations across PGE2-deficient Ptgs1/Ptgs2−/− BRAFV600E tumours from WT mice and PGE2-producing control BRAFV600E from WT mice, Ptger2−/−Ptger4fl/fl mice and Cd4crePtger2−/−Ptger4fl/fl mice revealed that the numbers of TCF1+ TILs were comparable among all groups." (PMID 38658748, 2024). "We therefore tested whether PGE2 controls the IL-2-mediated expansion of TCF1+ TILs sorted from PGE2-deficient Ptgs1/Ptgs2−/− tumours (identified as TIM-3−CXCR6− TILs)." (PMID 38658748, 2024). "Importantly, as for Ptgs2−/− singly deficient cells, a clear shift in the inflammatory profile toward increased expression of anti-tumor immune mediators was seen in tumors formed by Ptgs1/Ptgs2−/− doubly deficient cells." (PMID 26343581, 2015). "We first used neighbourhood analyses to survey the proportions of each cell type in the local neighbourhood of PIGR+ and PTGS1+ tumour cells." (PMID 38570491, 2024). "Remarkably, the most common neighbouring cell type was other tumour cells, with a significant proportion of cells neighbouring PTGS1+ cells also being PTGS1+ cells (90%, 80%, and 69% at the respective distances)." (PMID 38570491, 2024). "To examine the association of the subclones with other cell types, we removed all homotypic interactions between tumour cells and recalculated the proportions of heterotypic interactions involving the PTGS1+ and PIGR+ subclones and other cells." (PMID 38570491, 2024). "Increased production of the bioactive lipid PGE2 downstream of aberrant cyclooxygenase 1 (COX1; encoded by Ptgs1) and COX2 (encoded by Ptgs2) activity is observed in many human tumours and is associated with cancer progression and poor patient survival." (PMID 38658748, 2024). "Of the 13 validated differentially expressed genes, 7 and 6 were consistently identified by both technologies as significantly more highly expressed in the P5.1/PIGR+ or P5.2/PTGS1+ tumour subclones, respectively." (PMID 38570491, 2024). "Cyclooxygenases (Ptgs1, Ptgs2) are expressed primarily in epithelial to mesenchymal transition-like tumor cells, myeloid cells, neutrophils, and fibroblasts." (PMID 36277993, 2022). "The results showed that the growth rate of subcutaneous xenograft tumor cells with PROCR overexpression was suppressed when FASN or PTGS1/2 were inhibited." (PMID 35169126, 2022). "By microscopy, we confirmed reduced cDC1 numbers in tumor sections and further noticed decreased cDC1 clustering within Ptgs1/Ptgs2−/− BRAFV600E tumors transplanted into Rag2−/−Il2rg−/− mice or into NK cell-depleted mice." (PMID 29429633, 2018). "In a protein array, lysates of Ptgs1/Ptgs2−/− BRAFV600E early (day 4) tumors displayed 45-fold more CCL5 than COX-sufficient control tumor lysates and a minor (<2-fold) increase in CCL27A." (PMID 29429633, 2018). "Tumors formed by Ptgs1/Ptgs2−/− BrafV600E cells were noticeably smaller than their COX-sufficient counterparts even before adaptive immunity is expected to impact on tumor size." (PMID 26343581, 2015). "Analyses included real-time PCR of 45 angiogenesis-associated genes, immunohistochemistry (CD31, prostaglandin endoperoxide synthase 1/PTGS1) and assessment of tumour vascularisation by conventional histopathology." (PMID 24398114, 2014). "We found that xenograft tumours from mice treated with SP had significantly elevated expression of PTGS1 and PTGS2 mRNA compared to controls (3.1±0.1 fold; P<0.01 and 6.2±0.2 fold; P<0.001 for SP vs control for PTGS1 and PTGS2 respectively)." (PMID 22442729, 2012). "The inability of tumor lines to produce PGE2 renders them highly susceptible to cDC1-dependent CD8+ T-cell-mediated immune control, and researchers have exploited preclinical Ptgs1/Ptgs2-/- tumor models to characterize the mechanisms controlling cDC1 accumulation." (PMID 40410571, 2025).
tumor (continued). "Moreover, progressive outgrowth of control BRAFV600E tumours and efficient immune control of Ptgs1/Ptgs2−/− BRAFV600E tumours was unchanged following tumour transplantation to the same lymph drainage site." (PMID 38658748, 2024). "The results showed that some genes with the potential to promote tumor immune evasion, such as Ptgs1 and Dusp18, etc., were significantly enriched in all three analytical methods, which excludes the effect of different analytical methods on the differences in results." (PMID 38992029, 2024). "In order to study the expression patterns of genes in tumors and normal cell lines, PCR was used to detect the mRNA expression of genes, and the results showed that the expression of SPARCL1, HAND1, CLEC10A, PTGS1 genes in tumor group was significantly lower than that in the normal group." (PMID 35281077, 2022). "Principle component analysis (PCA) was used to reduce the dimensionality of the TCGA-COAD and READ data sets for the tumor and normal samples, as well as for sigmoid and transverse normal colon samples, based on the expression of PTGS1, PTGS2, PTGES3, and TERT." (PMID 31614548, 2019). "In NK cell-depleted mice, Ptgs1/Ptgs2−/− BRAFV600E tumors expressing XCL1 grew more slowly than mock-transduced cells, suggesting that XCL1-mediated recruitment of cDC1 can partially compensate for the loss of tumor immune control caused by NK cell ablation." (PMID 29429633, 2018). "In addition to increased density, cDC1 often formed multicellular clusters within Ptgs1/Ptgs2−/− BRAFV600E tumor tissue." (PMID 29429633, 2018). "Tumor molecular profiles showed few associations with clinicopathological variables, and these included downregulation of PTGDR and PTGS1 in older patients, overexpression of PTGER2, and hypermethylation of PTGS2 in right side tumors as compared with left colon." (PMID 26207152, 2015). "In parallel, upon RUNX2 knockdown, we have observed a predominant and strong downregulation of gene nodes known to be implicated in EOC tumorigenesis (PTGS1/COX1, FGF2, IL1A, Sapk, C/ebp, SELE, UBQLN1, PSAT1, ALDH1A1, GDF15, MTHFD2), including EOC tumor invasion/metastasis (MMP1, MMP13, Creb);." (PMID 24124450, 2013). "To investigate whether the two chemokines are necessary for cDC1 recruitment into tumors, we treated WT mice with neutralizing antibodies against CCL5 (αCCL5) and XCL1 (αXCL1) or isotype-matched control antibodies and implanted them with Ptgs1/Ptgs2−/− BRAFV600E tumor cells." (PMID 29429633, 2018). "This activation upregulates Ptgs1 and Ptgs2, the rate-limiting enzymes for prostaglandin synthesis, thereby increasing PGE2 production and suppressing anti-tumor immunity." (PMID 41383622, 2025). "This included PIGR in the subclone mapping to P5.1 and PTGS1 in the subclone mapping to P5.2, thus, we henceforth refer to these tumour subclones as PIGR+ tumour cells and PTGS1+ tumour cells, respectively." (PMID 38570491, 2024). "Compared to the normal tissue in the TCGA cohort, ACOX2 (P < 0.001), PTGS1 (P < 0.001), PTGS2 (P < 0.001), and PPARGC1A (P < 0.001) were downregulated, while HAO1 (P < 0.001) was upregulated in tumor samples." (PMID 38706909, 2024). "To identify the influence of lipid metabolism on tumor initiating potential in vivo, we administered FASN or PTGS1/2 inhibitors to mice and evaluated xenograft tumor growth regularly." (PMID 35169126, 2022). "qRT-PCR data confirmed that PGE2 expression-related genes including Ptgs1, Ptgs2, Hpdgs, and Hpdg were relatively higher in DXM/lactoferrin PMN-MDSCs compared to tumor PMN-MDSCs in the mouse model." (PMID 33637832, 2021). "As reported, control and Ptgs1/Ptgs2−/− BRAFV600E tumors were broadly equivalent in terms of total number of CD45+ cells, CD11c+MHCII+ cells, and tumor mass." (PMID 29429633, 2018). "Tumors formed by Ptgs1/Ptgs2−/− cells displayed markedly reduced global PGE2 levels, indicating a dominant role for tumor-derived over stroma-derived PGE2 in vivo." (PMID 26343581, 2015).